TNF (tumor necrosis factor)
Diseases named in the same sentence as TNF in open-access papers (continued):
Sharing a sentence is not in itself a finding about the gene and the disease.
tumor (continued). "Generally, M1 macrophages, activated by IFN-γ, LPS, or TNF-α, exhibit anti-tumor effects." (PMID 40908470, 2025). "Therefore, therapeutic interventions aimed at inhibiting IL-6 and TNF-α signalling pathways can potentially reduce inflammation and tumour proliferation." (PMID 40544399, 2025). "Moreover, NF‐κB activity‐induced expression of the pro‐inflammatory cytokines IL‐1β, IL‐6 and TNFα were also elevated in the hippocampus of these tumour‐bearing mice." (PMID 40172096, 2025). "Furthermore, cytokines that contribute to the tumor environment, including TNF and interferon-gamma, seem to make stromal cells more malleable." (PMID 41013839, 2025). "Furthermore, elevated levels of pro-inflammatory cytokines, such as IL-6 and TNF-α, drive chronic inflammation, creating a favorable environment for tumor cell growth and promoting the angiogenesis necessary for their vascularization." (PMID 39857306, 2025). "Tumor necrosis factor is widely accepted as a tumor-suppressive cytokine via its ubiquitous TNFRI." (PMID 40867267, 2025). "Tumor necrosis factor-α (TNF-α) is a pro-inflammatory cytokine and a potent anti-tumor effector." (PMID 40556785, 2025). "The cytokines IL-2 and TNF-α showed a significant correlation with tumor stage." (PMID 40869161, 2025). "This dual modulation of inflammatory mediators—suppressing chronic inflammation (IL-1β, IFN-γ) while inducing acute immune activation (IL-6, TNF-α)—may reprogram the tumor microenvironment toward an immune-permissive state." (PMID 41401147, 2025). "The TNFRII receptor (in contrast to TNFRI) diverts the tumor-inhibiting TNF into a tumor." (PMID 40867267, 2025). "However, chronic TNF-α stimulation can enhance tumor survival and proliferation through NF-κB activation, as well as metastasis through the induction of adhesion molecule expression, causing the negative effects of TNF-α to outweigh any benefit." (PMID 40227644, 2025). "In summary, within the depressive milieu, elevated TNF-α may significantly potentiate tumor cell survival, proliferation, and anti-apoptotic capacity through the PI3K/AKT pathway and its concerted modulation of NF-κB." (PMID 41000397, 2025). "Additionally, in comparison with the NZDP group, the TME exhibited more pronounced inflammatory characteristics following the combined treatment of NZDP combined with sonication, as evidenced by elevated levels of TNF-α cytokines at the tumor site." (PMID 39882403, 2025). "IL-1B and TNF expression were higher in the tumor group compared to the normal group." (PMID 39744500, 2025). "Additionally, tumor cells with high proliferative activity are more likely to undergo necrosis, releasing inflammatory mediators such as tumor necrosis factor, which can induce fever." (PMID 40606989, 2025). "Moreover, TNF‐α regulates vascular endothelial growth factor expression, facilitating tumor angiogenesis and supporting the progression of bone metastases." (PMID 40040540, 2025). "An agonistic TREM1 monoclonal antibody (PY159) could upregulate the secretion of inflammatory factors such as IFN-γ, CCL3, CCL4, IL-8, and TNF and increased tumor sensitivity to anti-PD-1 therapy in syngeneic mouse tumor models." (PMID 39744496, 2025). "Another subset of TANs exhibits anti-tumor features, characterized by TNFα, CCL3, and ICAM-1." (PMID 41009604, 2025). "TNF expression was higher in the tumor group as compared to the paracancerous group." (PMID 39744500, 2025). "Modulating cytokines like IL-6 and TNF-α could potentially shift the tumor microenvironment to support AR-targeting therapies." (PMID 40008000, 2025). "Similarly, knockdown of PRDX1 in RAW264.7 augmented the cytotoxicity of tumor‐infiltrating CD8+ T cells as shown by enhanced expression of TNF‐α and GzmB, concurrent with reduced expression of PD‐1." (PMID 41306557, 2025). "Nonetheless, mast cells may also support anti-tumor immunity by secreting IL-9 and TNF-α, particularly in MSI-H settings." (PMID 41244711, 2025).
tumor (continued). "TNF-α is primarily produced by activated macrophages and tumor cells, with contributions from fibroblasts, T lymphocytes, and natural killer cells, promoting its accumulation within the tumor microenvironment." (PMID 40251177, 2025). "Therefore, the TNF/TNFR axis likely plays a crucial role in sustaining Treg‐mediated immune suppression within the tumor microenvironment." (PMID 40977146, 2025). "After recognizing tumor cells, CIK cells enable to trigger cytotoxicity via releasing granzyme and perforin, secreting killing cytokines (IFN-γ and TNF-α), inducing tumor cells apoptosis via Fas-FasL pathway, and CD16-induced perform antibody-dependent cell-mediated cytotoxicity (ADCC)." (PMID 40624569, 2025). "IFN-γ, TNF-α, and IL-17 produced by γδT cells could enhance the immune response, promote tumor inflammation, and recruit other immune cells." (PMID 40226616, 2025). "Although anti-TNF-α therapy seems to mitigate the anti-PD-1-related AEs, without interfering with its antitumor effect, and PD-1 + TNF-α dual blockade might additionally reduce tumor resistance in vivo, combination therapy should be considered with caution." (PMID 38520533, 2025). "Higher serum TNF levels were associated with female sex (P = 0.026), older age (P < 0.001), BRAF mutation (P = 0.030), less frequent lymphovascular invasion (P = 0.044), and proximal tumor location (P < 0.001)." (PMID 40928327, 2025). "Furthermore, IgG1 plasma cells were shown to promote the secretion of key inflammatory cytokines, including TNF-α, IL-6, and IL-10, which not only sustain immune responses but also contribute to immune evasion and tumor progression." (PMID 41357192, 2025). "In cell cultures and animal models, NF-κB is activated and upregulated during inflammation, thus boosting the expression of several pro-inflammatory cytokines such as IL-1β, IL-6, COX-2, and TNF-α and altering tumor inflammatory microenvironment to promote tumor cell survival." (PMID 39834867, 2025). "The significantly lower circulating levels of TNF-α observed in the adjuvant cohort compared with the neoadjuvant cohort at T1 may be attributed to prior surgical tumor resection." (PMID 41153842, 2025). "Thus, IFN-γ and TNF-α contribute to an increase of CD8+ T cell production of chemokines that facilitate Treg infiltration into the tumor bed." (PMID 40553564, 2025). "It regulates several genes involved in the functions of the immune system, influences the phagocytic and tumor cell cytotoxic activity of macrophages and reduces the production of different proinflammatory cytokines, such as tumor necrosis factor alpha (TNF-α) and interleukin 6 (IL-6)." (PMID 41516276, 2025). "Moreover, we found that TNF-α is highly expressed in PTC tumor tissues compared with adjacent tissues, as assessed by immunohistochemistry (IHC)." (PMID 40360483, 2025). "The upregulation of TNF-α and IFN-γ, both hallmark cytokines of activated T cells, further indicates robust antigen-specific responses, as these molecules contribute to direct tumor cell killing and modulation of the immune microenvironment." (PMID 41376627, 2025). "TNF and its receptors are essential components of the tumor microenvironment (TME)." (PMID 40229245, 2025). "N1-type neutrophils, characterized by their anti-tumor phenotype, exhibit hypersegmented nuclei and high expression levels of factors such as tumor necrosis factor-α (TNF-α), intercellular adhesion molecule-1 (ICAM-1), vascular cell adhesion molecule-1 (VCAM-1), and CCL3." (PMID 40282474, 2025). "A common inflammatory cytokine found in the tumor microenvironment is TNF‐α." (PMID 39803280, 2025). "Similar to TAMs, TANs can shift between an anti-tumoral (N1) and a pro-tumoral (N2) phenotype, and Type I interferons (IFN-α and IFN-β) can promote their differentiation toward the N1 subset, reducing the pro-tumor impact of neutrophil extracellular traps and TNF-α expression." (PMID 40281554, 2025).
tumor (continued). "Parallel investigations revealed that integrating TLR4 and/or IFN-γ receptor signaling modules into CAR architectures stimulated macrophages to upregulate M1-polarization markers—including CD86, MHC class II (MHC-II), and TNF-α—while accelerating tumor regression in preclinical models." (PMID 41181137, 2025). "Additionally, Iwanicki and colleagues demonstrated that histotripsy can induce tumor apoptosis through the activation of caspase-3 via increased TNFα levels, effectively reducing tumor hypoxia in a neuroblastoma model." (PMID 40149252, 2025). "IKK inhibitors and proteasome inhibitors can suppress the nuclear translocation of NF-κB either directly or indirectly, leading to the downregulation of inflammatory cytokines (e.g., TNF-α, IL-6) and anti-apoptotic genes, thereby contributing to tumor microenvironment modulation." (PMID 41169368, 2025). "Tumor-secreted cytokines, IFNγ and TNFα, drive cardiac repair and suppress fibrosis." (PMID 41322654, 2025). "ELISA further confirmed a reduction of pro‐inflammatory cytokines TNF‐α and IL‐1β in tumor tissues." (PMID 41200213, 2025). "N1 TANs eliminate tumour cells by releasing ROS and TNF-α and activating CD8+ T-cell immunity." (PMID 41451221, 2025). "Additionally, NO and PGE2 concurrently stimulate proinflammatory cytokines, such as tumor necrosis factor alpha (TNF-α), interleukin (IL)-6, and IL-1β, which are significantly associated with tumor induction and progression." (PMID 39809510, 2025). "Functional validation experiments utilizing TNF-α, a potent NF-κ B pathway activator, demonstrated that pathway stimulation could effectively rescue the suppression of tumor cell proliferation, migration, and invasion induced by NMB knockdown." (PMID 40486508, 2025). "Additionally, M2-polarized TAMs secrete matrix-remodeling enzymes such as MMP-2, which facilitate tumor dissemination, while their production of IL-10 suppresses pro-inflammatory cytokines (TNF-α, IL-12, IL-1) and promotes tumor immune escape." (PMID 41394845, 2025). "Moreover, in HPV-positive BC patients, tumor tissue exhibits higher levels of IL-6, IL-17, TNF-α, and TGF-β, along with activation of NF-κB and STAT3." (PMID 41597595, 2025). "Furthermore, this specific lncRNA promotes TNF-α secretion by tumor cells, which activates PDPN+PDGFRα+ CAFs through the NF-κB pathway, forming a feedforward loop that amplifies neural invasion." (PMID 40861469, 2025). "Additionally, TNF-α levels increase in Schwann cells treated with different tumor cell lines or obtained from tumor-bearing animals." (PMID 40052442, 2025). "Additionally, the number of effector T cells expressing perforin, IFN‐γ, granzyme B, and TNF‐α were markedly reduced in the YP‐treated tumor microenvironment." (PMID 40108893, 2025). "Additionally, as the LG tumor expresses Eiger, a tumor necrosis factor (TNF) orthologue, the hemocytes recognize it via Eiger receptors on the cell surface, thereby inducing Turandot family proteins with anti-cancer effects." (PMID 40136638, 2025). "In addition to direct cytotoxicity, CTLs secrete pro-inflammatory cytokines such as IFN-γ and TNF-α, which exert antiproliferative effects on tumor cells and promote immune remodeling of the TME." (PMID 40660400, 2025). "These microbial-metabolic perturbations synergistically activate NF-κB and STAT3 signaling pathways, generating a pro-inflammatory cytokine milieu (IL-6, TNF-α, IL-1β) that establishes a tumor-promoting microenvironment through autocrine and paracrine cascades." (PMID 40919140, 2025). "TNF-α is an important inflammation-causing cytokine, mostly produced through macrophages, although it is also secreted by various malignant cells that promote tumor metastasis, migration, proliferation and invasion through activating TNF-α-induced PKCα-, NF-кB, and AP-1signaling pathway." (PMID 40294146, 2025).
tumor (continued). "Besides the common tumour-related terms such as TNF-α signalling via NF-κB and epithelial–mesenchymal transition, a major difference between Factor 34 and Factor 11 lies in the IFN (interferon) system." (PMID 40167331, 2025). "Therefore, we can conclude that mice that displayed sustained tumour growth had elevated concentrations of TNFα in the PFC." (PMID 40172096, 2025). "To assess whether pathological conditions influence TNFR2+ and TNF+ Tregs, we analyzed their frequency and phenotype within a tumor microenvironment, which is a context characterized by Treg expansion." (PMID 40977146, 2025). "It is driven by growth factors and inflammatory cytokines, that can be secreted by different stroma cells in the microenvironment, including tumor-associated macrophages (TAMs) such as tumor transforming growth factor β (TGFβ), epidermal growth factor (EGF), and tumor necrosis factor α (TNFα)." (PMID 41462963, 2025). "In addition, CD8 + T cell-derived EVs contain miR-298-5p, FasL, TNF-α, and PD-L1 to reduce the formation of mesenchymal tumor stromal cells including mesenchymal stem cells and CAFs, thereby mitigating melanoma progression." (PMID 40908470, 2025). "However, chronic TNF-α signaling can foster tumor progression by promoting angiogenesis, epithelial–mesenchymal transition, and immune evasion mechanisms." (PMID 40430212, 2025). "Tumor necrosis factor-alpha (TNF-α), a key pro-inflammatory cytokine primarily secreted by M1-polarized macrophages, plays a crucial role in maintaining chronic inflammation and contributing to tumor progression." (PMID 40430573, 2025). "Previous studies suggest that TNFα is involved in reduced macrophage infiltration in histopathological studies, indicating that TNFα may have a suppressive role alongside its tumor-promoting abilities." (PMID 40497976, 2025). "Additionally, AS-IV downregulated anti-inflammatory cytokines such as TGF-β, IL-10, and VEGF-A while upregulating pro-inflammatory cytokines including IFN-γ, IL-12, and TNF-α, thereby fostering a more immunologically active tumor milieu." (PMID 40417220, 2025). "This subtype also showed the strongest TNF-α–CA19-9 correlation (rho ≈ 0.79) in a subset analysis, suggesting intestinal-type cancers might drive a particularly robust inflammatory (TNF-α) and tumor marker (CA19-9) response." (PMID 40299527, 2025). "In cancer cells, TNF-α can have dual roles: it might induce apoptosis through extrinsic death receptors, but in an inflammatory milieu TNF-α often promotes survival by activating NF-κB and other pathways in tumor cells." (PMID 41002416, 2025). "Additionally, mast cells directly kill tumour cells through the release of TNF‐α and reactive oxygen species." (PMID 41001838, 2025). "Remarkably, CPD-L1 plus AZA combination therapy could significantly upregulate the levels of IFN-γ, IL-12p70, TNF-α, and downregulate the levels of IL-6, IL-10 in tumor tissues." (PMID 40994623, 2025). "Moreover, CAR-T cells are highly susceptible to inducing cytokine release syndrome (CRS) through the substantial release of TNF-α, IL-1β, and IL-6 upon targeting tumor antigens." (PMID 40573985, 2025). "Th1 cells produce IFN-γ, IL-2, and TNF-α, playing a major role in tumor immunity." (PMID 40822970, 2025). "Furthermore, TNF-α levels were significantly elevated (P < 0.001) in CM from tumor tissue of VS patients who underwent subtotal resection (STR) rather than gross total resection (GTR)." (PMID 39923035, 2025). "TNF‐α can also induce elevated levels of vascular endothelial growth factor, which is essential for providing oxygen and nutrients to tumor cells and plays a critical role in tumor metastasis." (PMID 40620232, 2025).
tumor (continued). "Upon activation, they produce IFN-γ, granzyme B, and TNF and can contribute to tumor control." (PMID 40660400, 2025). "These cells would carry an epigenetic memory of training and could secrete high levels of TNFα/IL-1 upon encountering the tumor." (PMID 40227782, 2025). "Notably, MMP1 activated macrophages via the ANXA1-FPR3 pathway, triggering TNFα secretion, which further enhanced NF-κB activation and tumor progression." (PMID 40394037, 2025). "In addition, TNF-α, IL-1β, and IL-6 have been demonstrated to suppress cell mediated immunity and promote intravascular tumor cell adhesion." (PMID 40427164, 2025). "Cytokines, such as IFN-γ and TNF-α, are potent immunomodulatory molecules that can effectively trigger tumor cell death and exert powerful antitumor effects through multiple mechanisms, including the enhancement of NK cell activity and the up-regulation of adhesion molecules on tumor cells." (PMID 41102150, 2025). "With TNFα expression in the lamina propria also higher in patients with progressing OSCCs, neutrophils may in fact promote tumor formation under certain conditions." (PMID 40724900, 2025). "Importantly, we found that TNF-α levels differed according to tumor stage and histopathology, pointing to its potential role as a marker of disease severity." (PMID 40299527, 2025). "TNF-α interaction has a crucial role in promoting tumor development, invasion, and metastasis." (PMID 39570546, 2025). "Although CD4+ T cell infiltration was not significantly changed, TNBCvax vaccination enhanced Th1-associated cytokine production (IFNγ and TNFα) which is suggesting a functional shift in CD4+ T cell activity that supports overall immune activation and CD8+ T cell-mediated tumor control." (PMID 40969744, 2025). "IL-12 and TNF-α, secreted by M1-type macrophages, are typical pro-inflammatory factors that activate and recruit additional immune cells to participate in tumor killing, while IL-10, secreted by M2-type macrophages, inhibits the inflammatory response and attenuates immune function." (PMID 41383334, 2025). "HPSCC tumor models showed differences in TNFα levels across all experimental groups." (PMID 41401057, 2025). "The mechanism of antitumor action of the indium complex of porphyrin consisted of oxidative stress and a decrease in the secretion of nuclear factor erythroid 2-related factor 2 (Nrf-2) and an increase in the secretion of tumor necrosis factor TNF-α in A2780 tumor cells." (PMID 41226774, 2025). "Immunological analysis revealed significantly increased levels of DCs and CD8+ T cells in both tumors and their draining lymph nodes in the treated group, accompanied by elevated levels of immune-promoting cytokines such as IL-12 and TNF-α, ultimately leading to marked tumor suppression." (PMID 41394807, 2025). "Furthermore, TNF-α and other inflammatory markers were more highly expressed in the less stem-like tumor cells, indicating a possible role of inflammation in promoting differentiation." (PMID 40806540, 2025). "Furthermore, anti-tumor mechanisms such as induction of cytotoxic T lymphocytes (CTLs) and tumor necrosis factor-α (TNF-α) secretion, downregulation of Ki-67s, and decreasing PD-1+ T cells have also been identified." (PMID 41170411, 2025). "This scenario reflects the reality that A20−/− cancer cells within a tumor microenvironment may misinterpret low TNF signals as high and trigger antiapoptotic or proliferative signaling." (PMID 41509253, 2025). "Similarly, the dysregulation of NF-kappa B and TNF signaling contributes to the inflammatory tumor microenvironment, further inhibiting antitumor immune responses." (PMID 40647469, 2025). "Importantly, to specifically assess tumour-intrinsic mechanisms, we deliberately avoided pre-stimulation of endothelial cells with TNF-α or other cytokines, which are often used to mimic inflammatory conditions in extravasation models." (PMID 40890143, 2025).